CD4 (CD4 molecule)
Diseases named in the same sentence as CD4 in open-access papers (continued):
Sharing a sentence is not in itself a finding about the gene and the disease.
infection (continued). "This increase in checkpoint inhibitors is also seen in animal models of HIV‐infection, with PD‐1 expression increasing on CD4+94 and CD8+ T cells, and Tim‐397 and TIGIT91 expression increasing on CD8+ T cells following infection of nonhuman primates (NHPs) with simian immunodeficiency virus (SIV)." (PMID 39248154, 2024). "Overall, this paraclinical observation is not uncommon during the course of infection in the daily routine, but this finding was presented for the first time for CAP in PLWH in a prospective clinical study, although relevant CD4 data were available for only 27, 54, 30, and 34 cases, respectively." (PMID 37423969, 2024). "Importantly, post vaccination, especially after the third dose, CD4+ T cells tend to skew toward a Th1‐type response characterised by IFN‐γ secretion, rather than Th2, Th17 or TFH responses upon Omicron infection." (PMID 38224200, 2024). "Interestingly, spike-specific CD4 and CD8 T cell levels only correlated in individuals with previous infections, whereas no such correlation was observed among non-infected individuals." (PMID 38594497, 2024). "Here, we describe experiments comparing gene expression between CD4+ T cells from acutely HIV-1–infected men and women in Zambia who were ART naïve at the time of sample collection, allowing for comparison of natural infection in the absence of treatment." (PMID 39902043, 2024). "Although the presence of multifunctional Th1-polarised CD4+ T cells co-expressing IFN-γ, TNF and IL-2 has been considered a CoP against M. tuberculosis infection, vaccines inducing these responses do not consistently protect against infection in human trials." (PMID 38400112, 2024). "Notably, however, neither the transfer of parasite-primed CD4+ or CD8+ T cells nor the total absence of CD4+ or CD8+ T cells impacted parasite load at the site of infection during the initial 6 to 7 days of infection." (PMID 36695605, 2023). "Thus, our Stat1T385M/+ mouse model recapitulates several features of abnormal CD4 T cell differentiation seen in STAT1 GOF patients, but in the absence of infection." (PMID 37275873, 2023). "Indeed, the clonal overlap was increased only in CD4+ and CD8+ effector T cells between day 8 and 40 post-infection and not in the other T cell states and between PBS and infected mice." (PMID 37325645, 2023). "In contrast, CD4+ and CD8+ T cells targeting non-spike proteins remained functionally static and waned over time, and only minimal effects were observed in healthy vaccinated donors experiencing breakthrough infections with SARS-CoV-2." (PMID 38064569, 2023). "Furthermore, no clear CD4 or CD8 T cell activation, in relation to CD28 or CD127 expression, was observed post-infection." (PMID 37012228, 2023). "IFN produced by CD8+ T cells alone was adequate for fortification, even in the absence of CD4+ T cells and B cells, suggesting that CD8+ T cells may also give a shield against infection with additional orthopoxviruses." (PMID 37533932, 2023). "Moreover, recent evidence has also suggested that the SARS-CoV2-specific CD4+ and CD8+ T cells can protect the experimental mice from infection, even in the absence of neutralizing antibodies." (PMID 37762235, 2023). "Thus, the high expression of GalCer and CCR5 by jejunal epithelial cells, which express neither CD4 nor CXCR4, would be the basis of the transmission of HIV-1 CCR5 tropic viruses during primo-infection via the mucosal route." (PMID 37511488, 2023). "The nuclear localization signal (NLS)-TDP-43 mutant was not able to control the HIV-1 viral production and infection and could not stabilize HDAC6, as previously reported in CD4+ T permissive cells." (PMID 37108826, 2023). "As the CD4+ TEMRA cell compartment increases with age, there may be some link between TEMRA cells and the lack of response to infection and vaccination in the elderly population." (PMID 37106796, 2023).
infection (continued). "Our study found that in the natural infection status without MTB-specific stimulation, the IFN-γ production in CD8+ T cells in the TB group was still enhanced, but the production of IFN-γ in both CD4+ and CD8+ T cells in the HT group were not increased." (PMID 37483385, 2023). "Thus, our data demonstrate that P1 mRNA has the capability to activate both CD4+ and CD8+ T cells in participants, irrespective of their past infection status, resulting in a preferential production of IFN-γ and TNF-α." (PMID 38051989, 2023). "This information could prove useful in expanding upon the findings of the data presented, in which CD4+ and CD8 + T-cell infiltration was observed, yet the precise role the cells played at the site of infection was not studied." (PMID 37386155, 2023). "Surprisingly, the enhanced production of CD4+ and CD8+ T cells did not accelerate the vaginal clearance or total burden, suggesting that enhancing Th1 responses to whole Chlamydia does not necessarily support the clearance of the infection." (PMID 38441219, 2023). "Further, correlation with disease severity revealed that the CD4+ response best predicted disease severity, not the antibody response, suggesting that the T cell arm of adaptive immunity is critical in clearing SARS-CoV-2 after infection." (PMID 35401519, 2022). "In addition, cell-to-cell transfer of R5 viruses, including viruses expressing the prototypic non-M-tropic JR-CSF Env, is less dependent on CD4 and CCR5 cell-surface expression levels on MDMs than infection with cell-free viruses." (PMID 35622876, 2022). "The frequency of intracellular IL-10 expressing CD4+ suppressive T cells to HBV core peptides was higher in HBV infected individuals with OBI (0.12%), CHB (0.11%), or resolved infection (0.1%), respectively, than in HBV non-infected individuals (0.06%) (P < 0.05)." (PMID 35464946, 2022). "None of the sera showed strong competition with PGT145, CD4-IgG2, FZ019.2, or K11 for binding to SIVmac239 SOSIP.664, suggesting that the neutralizing epitopes are relatively poorly targeted in natural infection and consistent with relatively low serum neutralizing titers." (PMID 36068229, 2022). "Interestingly, some features of non-progressing SIVsmm infection in SMs—low immune activation despite high viremia and low CCR5 density on CD4+ Tcm cells—were observed in a pediatric HIV non-progressor cohort from South Africa." (PMID 36713371, 2022). "However, despite the conceptual appeal of this model, protection against C. muridarum within the FRT is CD4-dependent and mice lacking cytotoxic CD8 T cells control infection." (PMID 35196366, 2022). "Moreover, both CD4+ and CD8+ T cells were induced after infection, and were detectable even in the absence of virus-specific antibodies." (PMID 35214700, 2022). "Within the S-specific T cell response, CD8/CD4 ratios were similar between BTI and non-BTI within the first two weeks of infection (0.2 - 0.4), while median CD8/CD4 ratios were 2- to 5-fold higher in BTI versus non-BTI versus during weeks 3 (p=0.06), 4 (p=0.06), and 5 (p=0.18)." (PMID 36582222, 2022). "Serum antibodies, memory B cells, memory CD4 T cells, and CD8 T cells were all characterized in individuals with asymptomatic or symptomatic infections followed by vaccination or no vaccination to determine the impact of symptomatology on immunological memory in this cohort of young adults." (PMID 36168391, 2022). "Furthermore, we did not detect significant differences in numbers of CD4, CD8 or virus-specific S510+/Db tetramer+ CD8 T cells throughout infection." (PMID 36333761, 2022). "The T cell depleted animals were not excluded based on a detailed analysis of the humoral response in these macaques, which suggested that neither CD4+ nor CD8+ T cells were critical for the development of anamnestic antibody responses, neutralizing antibodies, or protection from re-infection." (PMID 35404959, 2022).
infection (continued). "Along with the negative effects of type I IFN induced by LCMV Arm infection in TB pathogenesis depicted above, we next investigated whether the effect of type I IFN on CD4+ T cell proliferation and functionality occurred in an Mtb Ag-specific manner in vivo." (PMID 35672321, 2022). "Similarly, we observed PD-1 upregulation on CD4+ T cells but not CD8+ T cells or B cells in the ankle joints two, four, and eight weeks post-infection." (PMID 36265003, 2022). "Additionally, we did not characterize the phenotypic memory differentiation for SARS-CoV-2 specific CD4+ and CD8+ T cell responses, nor test SARS-CoV-2-specific T cells responses in the breakthrough infection cohort." (PMID 35608053, 2022). "As also observed using AraC, TNTi did not have any effect on low-level productive infection of DCs using nonopsonized HIV, while the high transmission of the virus from HIV-loaded DCs to CD4+ T cells was significantly impaired, indicating the strong involvement of TNTs in virus transfer." (PMID 35204813, 2022). "It is not clear in particular how these cells escape infection and depletion by HIV, considering that high-affinity CD4 + T cells are exquisitely sensitive to Gag antigens, and are thus likely the first to become activated and productively infected upon virus encounter." (PMID 35082297, 2022). "In contrast to SIVmac239, in SIVmac239ΔGY infection CD4+ T cells are not depleted in blood or gut, GALT infection is only transient, there is no microbial translocation or chronic immune activation, and animals remain healthy for months to years as elite controllers." (PMID 35714165, 2022). "However, the global phenotype of CD4 T cells, CD8 T cells, double-negative (DN) T cells, or NK cells was not affected by infection, as indicated by the low level of JS divergence when different conditions were compared." (PMID 34160241, 2021). "If B cell-mediated trans infection of TN is an important mechanism by which these cells become infected with HIV-1, then it is plausible that NP have a reduced or absent level of HIV-1 DNA in this CD4+ T cell subset." (PMID 33688006, 2021). "Consistent with a minimal impact of Rb treatment in enhancing NP396–404-specific CD8 T cells following acute LCMV-Arm infection, no alteration in the number of IFNγ-producing NP396–404-specific CD8 T cells was observed in Rb treated LCMV-Arm infected CD4−/− mice." (PMID 34206262, 2021). "However, the proportion of total CD4 T-cells and CD4+CD44+ activated T-cells out of total CD3+ T-cells did not change from 14- to 100- days post-infection." (PMID 35186781, 2021). "Importantly, 26% of subjects with pre-existing CD4+ T-cell reactivity went on to develop PCR-verified infection by TP5, compared to 20% of subjects without pre-existing CD4+ T-cell reactivity." (PMID 34795668, 2021). "Further evidence demonstrated that CD4+ and CD8+ T cells lacking GPX4 failed to expand and could not prevent immunity to infection." (PMID 35154262, 2021). "Additionally, CD4+ but not CD8+ Treg cells were suppressed by IL-6, allowing pathogen clearance and host survival in virus-induced infection." (PMID 34696231, 2021). "We observed higher levels (>10%) of PD‐1hi expression on CD4+T cells and lower levels of PD‐L1hi (≤1%) on IgM+ CD19+ B cells in patients with HCV‐related MC compared to patients with HCC without HCV‐infection, suggesting an alteration in the control of B cell‐T cell interaction in our MC cases." (PMID 32937024, 2021). "In line with our previous data infection of BALB/c mice with S. ratti did not alter the frequency of conventional Treg, defined as Foxp3+ T cells within the CD4+ T cells, while the frequency of Foxp3+ cells increased in infected F1 and C57BL/6 mice compared to non-infected mice." (PMID 33452272, 2021). "Thus, FGF-1 treatment did not affect the functional capability of CD4 and CD8 T cells at the site of infection." (PMID 34054858, 2021).
infection (continued). "Also, at later time points of the acute infection (day 34), when the virus is cleared and the cellular immune response returns to baseline, no quantitative or qualitative differences of LCMV CD4+ and CD8+ T‐cell response were detected in miR‐21 KO mice." (PMID 34584693, 2021). "The first factor was not correlated with median first CD4 count, suggesting our quality measure captures aspects of care for patients already in care, but does not capture the extent to which facilities are able to screen patients for HIV earlier in infection." (PMID 33789340, 2021). "However, a similar increase was not reflected in the CD4+ and CD8+IL-17+ T cells at week 1 post infection in the low dose group." (PMID 34484203, 2021). "While some early studies described a non-productive infection, other reports indicated productive HIV-1 replication in astrocytes at low levels by the mechanisms that involve exosomes from infected trafficking CD4 cells or from direct cell to cell contact." (PMID 34325716, 2021). "CD4+, and CD8+ T cells, plasma cells did not change during rDEN2Δ30 infection." (PMID 34031380, 2021). "We did not account for the CD4 + counts, viral loads, ART use or duration of infection in the HIV positive women included in this study and these may have affected our findings for HIV positive women." (PMID 33154533, 2020). "However, the frequencies of cytotoxic marker expressing CD4+, CD8+ T cells, and NK cells at the site of infection is not known." (PMID 33101317, 2020). "Both CD4+ and CD8+ HCV-specific T cells are commonly present in liver tissue and in peripheral blood, however, in most patients, these cells are unable to clear the infection and do not prevent re-infection with HCV." (PMID 32722372, 2020). "Therefore, although the absence of T-bet results in defective CD4+ Th1 responses, TNF-α production is still maintained in these cells and CD8+ T cells are still able to produce significant levels of IFN-γ after STm infection." (PMID 32591391, 2020). "Although infections with enteroviruses were not more frequent in PLHIV, a higher diversity of enteroviruses, including rare and zoonotic types, was predominantly detected among HIV-positive individuals with a low CD4+T cell count." (PMID 32079128, 2020). "Alternatively, there is evidence from P. falciparum, that the PfEMP1 binding domain, CIDR-1α, stimulates CD4+ T-cells non-specifically through TCR-independent pathways, and that regulatory T-cell (Treg) proliferation during an infection can be induced in an antigen non-specific manner." (PMID 33329568, 2020). "However, the CD4+CD44+IFN-γ+ T-cell (R = 0.6789, p < 0.0001) responses to ESAT-6 correlated negatively with bacterial load post-infection, but not pre-infection." (PMID 32545304, 2020). "However, ART alone does not cure the infection, primarily because HIV can persist in stable long-term reservoir cells including latently-infected CD4 + T cells." (PMID 32252791, 2020). "We curated 46 CPSF6(+) RIGs from multiple cell types (HEK293T, HOS, MDM, and CD4+ T cells) and 30 CPSF6(−) RIGs from these same cells when infection occurred in the absence of the CA–CPSF6 interaction (i.e., N74D or A77V CA mutant viruses, or WT CA infection of CKO cells)." (PMID 32665593, 2020). "In Gudair-vaccinated sheep, vaccine-protected sheep displayed increased antigen-specific proliferation of peripheral blood CD4+ and γδ+ T cells, and B cells at 13-21 weeks post oral MAP challenge when compared to Gudair-vaccinated sheep that did not control infection." (PMID 33329565, 2020). "By 42 d following percutaneous infection, we observed in C57BL/6 mice grossly visible liver granuloma, significantly increased CD4 and CD8 T cell numbers in spleen, regardless of the significant drop of CD4 T cells in peripheral blood." (PMID 33347431, 2020).
infection (continued). "Because HSPCs generally have limited surface expression of CD4, their abnormalities in HIV infection could be largely explained as an indirect effect of HIV infection, rather than the results of direct infection of HSPCs." (PMID 32154191, 2020). "Interestingly, in splenocytes of infected SD rats we observed no significant changes in total T cells or in CD4, CD8 subsets following infection in terms of cell count." (PMID 33347431, 2020). "Finally, although LECs that archive viral antigens upregulate MHCII molecules upon infection, it seems that they are not able to directly present these antigens through MHCII but instead transfer them to DCs for presentation to CD4+ T cells." (PMID 33096748, 2020). "Although we observed a reduction in the MFI of CCR5 on CD4 T cells, likely due to its reported co-expression with S1P receptor 1 in primary CD4 T cells, FTY720 inhibited infection irrespective of HIV-1 tropism, indicating a mechanism independent of coreceptor utilization." (PMID 32790802, 2020). "But while vaccination or adoptive transfer of SARS-CoV-specific CD4 and CD8 T cells could lead to the amelioration of clinical disease, it is still not clear whether infection-generated virus-specific T cells have an equally protective role against SARS-CoV-2." (PMID 33302366, 2020). "Since this is a critical issue for understanding the role of envelope PtdSer in the host range/tropisms of HIV-1, we examined the role of PtdSer-binding molecules in HIV-1 binding and infection in the presence and absence of the HIV-1 cognate receptor (CD4) and co-receptor (CCR5)." (PMID 31638994, 2019). "In comparison with non-infectious SLE patients (387.9±261.6/μL), CD4+T cells count decreased significantly in infectious SLE patients (217.8±150.4/μL) (P<0.05), and it was negatively correlated with infection-related indicators including PCT (r=−0.573, P=0.041) and CRP (r=−0.596, P=0.032) levels." (PMID 30994732, 2019). "Non-activated (CD25−, CD69−) CD4+ T cells were highly permissive to entry by X4-tropic HIV, with viral entry detected in 65% ± 11% of resting CD4+ T cells at the multiplicity of infection used (top)." (PMID 30943397, 2019). "In fact, because spleen IFN-γ was reduced to the same level as non-infected mice on day 7 after infection in CD4+ T cell-depleted mice, most IFN-γ may be produced by CD4+ T cells, at least in the early stage of infection." (PMID 31608052, 2019). "However, in the case of HIV-1 recognition, viral entry via Siglec-1 does not lead to the productive infection of DCs as it happens with EBOV, but favors the transfer of trapped viruses to bystander CD4+ T cells." (PMID 31861617, 2019). "The blood levels CD4+ T-cells and soluble CD40L (sCD40L) could be variable during stages of CD4+ T-cell activation by HIV-1 or other infection, but have not seen variability in our normal study population." (PMID 31521107, 2019). "The percentages of CD4+ CD25+ FoxP3+ T-reg cells increased from 21% in noninoculated middle ear fluid to 70% in day 3 and day 7 NTHi-infected middle ear fluid, confirming the induction of T-reg cells by sustained NTHi infection." (PMID 31548315, 2019). "Without CD4 T cells, a significant decrease in the frequency and total number of GP33-tetramer positive Tcf7−/− CD8 T cells in the spleen and liver tissues was observed compared to that in WT counterparts at day 8 post Cl13 infection." (PMID 30814995, 2019). "Similarly, on day 5 and irrespective of infection status, PHA induced significantly elevated expressions of CD38+HLA-DR+ and CD38+HLA-DR-, but not CD38-HLA-DR+ on CD4+ T cells compared to the unstimulated infected control (p ≤ 0.0001)." (PMID 31396221, 2019). "While some mice in both the depleted and control groups demonstrated some form of hind limb weakness that was first seen on day seven post infection, we noted whole body tremors and muscle shaking uniquely in the ZIKV infected CD4-depleted mice that we did not observe in the control group." (PMID 30212537, 2018).